LPCAT1 (lysophosphatidylcholine acyltransferase 1)
Diseases named in the same sentence as LPCAT1 in open-access papers (continued):
Sharing a sentence is not in itself a finding about the gene and the disease.
gastric cancer (14 papers, 2016 to 2025). A primary or metastatic malignant neoplasm involving the stomach. "The concordance between transcriptomic signatures and protein-level validation by IHC preliminary establishes LGALS3 and LPCAT1 as functionally relevant biomarkers in gastric cancer immunotherapy response." (PMID 40723289, 2025). "Increased levels of saturated phospholipids are present in clear cell renal cell carcinoma, HCC and gastric cancers, which is aligned with LPCAT1 enzyme activity." (PMID 38921447, 2024). "For example, the ratio of lysophosphatidylcholine (LPC) to phosphatidylcholine (PC) was indicated the dysregulation of lysophosphatidylcholine acyltransferase 1, that play essential roles during the tumorigenic process of gastric cancer." (PMID 32957957, 2020). "Based on our previous study, we further demonstrated that the expression of LPCAT1 was upregulated in EC with more IHC histologic sections, which is consistent with that of AML and gastric cancer." (PMID 35880567, 2022). "Consistent with LPCAT1 enzyme activity, the level of saturated phospholipids is increased in clear cell renal cell carcinoma, HCC, and gastric cancers." (PMID 33530546, 2021). "Ueharaet al. found that LPCAT1 expression level was highly upregulated in gastric cancer lesions compared to the level in nonneoplastic mucosa." (PMID 35880567, 2022). "LPCAT1 was highly expressed in gastric cancer lesions compared to non-neoplastic mucosal tissues, predominantly in patients with differentiated adenocarcinomas." (PMID 29348849, 2017). "Levels of LPCAT1 were higher in gastric cancer tissue than in adjacent non-neoplastic mucosa, and this overexpression was predominant in differentiated adenocarcinomas, so LPCAT1 could play important roles in the tumorigenesis of differentiated adenocarcinomas compared to undifferentiated ones." (PMID 27916803, 2016).
lung adenocarcinoma (11 papers, 2017 to 2025). A carcinoma that arises from the lung and is characterized by the presence of malignant glandular epithelial cells. "In lung adenocarcinoma, high LPCAT1 expression is linked to the formation of brain metastasis, implicating its involvement in this metastatic process." (PMID 38893234, 2024). "Finally, elevated LPCAT1 expression in patients with lung adenocarcinomas was associated with a poor clinical outcome." (PMID 30791942, 2019). "Resistance to gefitinib in lung adenocarcinoma is caused by increased activation of the EGFR-phosphatidylinositol 4,5-bisphosphate 3-kinase (PI3K)-protein kinase B (PKB) signaling pathway by LPCAT1." (PMID 38893234, 2024). "Reduction of LpCat1 level in lung adenocarcinoma obviously restrained tumor growth and brain metastases in vivo." (PMID 34178664, 2021). "Analysis of THPA revealed that LPCAT1 expression was relatively higher in lung cancer than in other 16 tumors, and the LPCAT1 expression in lung adenocarcinoma was significantly higher than in lung squamous cell carcinoma." (PMID 30791942, 2019). "Lpcat1 promotes brain metastasis of lung adenocarcinoma by upregulating the PI3K/Akt/myc pathway." (PMID 35634481, 2022). "This study showed that LPCAT1 works as a regulator of cell metastasis and may serve as a novel therapeutic target for BM in lung adenocarcinoma." (PMID 30791942, 2019). "To further understand the heterogeneity and meaning of LPCAT1 expression in NSCLC primary tumors and metastatic lesions, we obtained and analyzed the lung adenocarcinoma brain metastases single cell transcriptome sequencing dataset (GSE131907)." (PMID 38589859, 2024). "This study was aimed to identify genes involved in lung adenocarcinoma (LUAD) brain metastasis, and look into the role of LPCAT1 in LUAD progression." (PMID 30791942, 2019). "In addition, the expression of c-myc, which is upregulated by LPCAT1 in patients with lung adenocarcinoma, was not enhanced compared with EGFR/PI3K in ESCC cells, which suggests that LPCAT1 may regulate cholesterol synthesis in ESCC cells primarily through these pathways." (PMID 34518524, 2021).
lung carcinoma (11 papers, 2013 to 2025). "Importantly, this means that for the first time, over-expression of ERGIC3 and LPCAT1 have been linked to lung cancer." (PMID 23374247, 2013). "Single-cell RNA sequencing of LUAD brain metastases confirmed significantly elevated LPCAT1 expression in lung cancer cells at BM sites compared to primary lung tumor cells." (PMID 40028322, 2025). "Upregulation of LPCAT1 in NSCLC has been associated with an increased incidence of BM, while LPCAT1 inhibition effectively curbs lung cancer cell proliferation and metastasis." (PMID 40028322, 2025). "Conversely, downregulating LPCAT1 significantly suppresses the proliferation and metastasis of lung cancer cells." (PMID 38589859, 2024). "We then encapsulated the engineered exosomes armed to EGFR with LPCAT1 siRNA (siLPCAT1) and intravenously injected them into a mouse model of lung cancer BM." (PMID 38589859, 2024). "LPCAT1 was supposed to play a pro-tumoral role in NSCLC by promoting lung cancer cell proliferation and migration." (PMID 38589859, 2024). "In this study, we firstly confirmed significant upregulation of LPCAT1 in BM sites compared to primary lung cancer by analyzing scRNA dataset." (PMID 38589859, 2024). "Previous studies have emphasized the important role of Lpcat1 in lung cancers, and recent studies have shown that Lpcat1 also plays a role in neurological diseases." (PMID 37292937, 2023). "We found that LPCAT1 expression was relatively higher in patients with lung cancers than in those with other 16 tumors." (PMID 30791942, 2019). "In this study, by searching online databases, we acquired the data concerning the LPCAT1 expression in the tumor tissues from lung cancer patients and in NSCLC cell lines." (PMID 30791942, 2019). "By employing RNA-Sequencing (RNA-Seq), we confirmed that LPCAT1 was more highly expressed in lung cancer tissues in patients with brain metastasis than in their counterparts without BM." (PMID 30791942, 2019). "Our results indicated that LPCAT1 was highly expressed in lung tumor tissues, and the LPCAT1 expression was even higher in lung tissues from lung cancer patients with brain metastasis." (PMID 30791942, 2019). "Importantly, our data showed that LPCAT1 siRNA-loaded scFv-coated exosomes (exoscFv/siLPCAT1) exerted potent anti-tumor effects in metastatic brain tumors from lung cancer." (PMID 38589859, 2024). "Lysophosphatidylcholine acyltransferase 1 (LPCAT1), a cytosolic enzyme that converts lysophosphatidylcholine into phosphatidylcholine, is highly expressed in multiple cancer types, including lung cancer, glioblastoma, endometrial cancer, and esophageal carcinoma." (PMID 38589859, 2024). "Finally, circZCCHC6 has been recently described to regulate lysophosphatidylcholine acyltransferase 1 (LPCAT1) levels via miR-433-3p in lung cancer." (PMID 36297470, 2022). "LPCAT1 has been shown to make lung cancer cells more sensitive to cisplatin, but how it alters the chemosensitivity of CRPC cells is unknown." (PMID 33137125, 2020). "Our survival results suggested that elevation of LPCAT1 might be involved in the carcinogenesis and brain metastasis of lung cancer." (PMID 30791942, 2019). "Moreover, search of the THPA dataset showed the positive rate of LPCAT1 was up to 80% in lung cancer tissues." (PMID 30791942, 2019). "By searching tumor-related online databases and examining the gene expression in primary loci and adjacent tissues in healthy subjects and lung-cancer patients, we found that LPCAT1 was highly expressed in pulmonary tissues and its over-expression was correlated with the poor prognosis of NSCLC." (PMID 30791942, 2019). "Over-expression of two genes (ERGIC3 and LPCAT1) had not been previously linked to lung cancer." (PMID 23374247, 2013). "High expression of SERPINE1 and STC2 in lung cancer tissues of NSCLC patients (n = 5) and low expression of LPCAT1 in the NSCLC group were confirmed at the mRNA level compared to those in the normal lung tissues (n = 5)." (PMID 35634481, 2022).
lung carcinoma (continued). "In the first stage of the screening for 16 genes, two novel lung cancer-related genes (ERGIC3 and LPCAT1) were found." (PMID 23374247, 2013). "Through q-RT-PCR analysis, we found six genes (DDR1, HSP90B1, SDC1, RPSA, ERGIC3, and LPCAT1) significantly up-regulated and two genes (GPX3 and TIMP3) significantly down-regulated in the lung cancer tissues." (PMID 23374247, 2013). "LPCAT1 has been shown to significantly promote brain metastases of lung cancer by upregulating the PI3K/AKT/MYC pathway, making it a promising target for treating BM in lung cancer patients." (PMID 38589859, 2024). "LPCAT1 had never been reported in cervical cancer but was reported to promote gefitinib resistance through upregulation of the EGFR/PI3K/Akt signaling pathway in lung carcinoma, and it has been recognized as a promising prognostic biomarker in liver cancer." (PMID 38656879, 2024).
clear cell renal cell carcinoma (9 papers, 2017 to 2026). "Moreover, the alteration of the phospholipid component regulated by LPCAT1 promotes cell proliferation and membrane fluidity, thus causing the occurrence and development of clear cell renal cell carcinoma." (PMID 34419067, 2021). "Overexpression of LPCAT1 has been shown to increase cell proliferation, migration, and metastasis in clear cell renal cell carcinoma and HCC cell lines." (PMID 33530546, 2021). "In clear cell renal cell carcinoma cells, depletion of LpCat1 decreased PCs, inhibited biological phenotype of cancer cells, and induced cell cycle arrest at G0/G1 phase." (PMID 34178664, 2021). "Moreover, Duet al. found an up-regulation of LPCAT1 in clear cell renal cell carcinoma (ccRCC) tissues and demonstrated that LPCAT1 promotes ccRCC progression probably by transferring lysophosphatidylcholine (LPC) into phosphatidylcholine (PC)." (PMID 35880567, 2022). "In clear cell renal cell carcinoma, ACLY expression is upregulated through HIF-2α/LPCAT1/FBXW7 and VHL/PPARγ axes, promoting lipid synthesis, tumor proliferation, and metastasis." (PMID 41958067, 2026). "Elevated levels of cell proliferation, migration and metastasis in clear cell renal cell carcinoma and HCC cell lines all result from overexpression of LPCAT1." (PMID 38921447, 2024).
colorectal cancer (8 papers, 2013 to 2023). A primary or metastatic malignant neoplasm that affects the colon or rectum. "Overexpression of LPCAT1 was recently described in colorectal cancer, prostate cancer, lung cancer and clear cell renal cell carcinomas." (PMID 31533087, 2019). "In addition, overexpression of LPCAT1 also led to a significant growth advantage in cultured colorectal cancer cells." (PMID 34518524, 2021). "LPCAT1 overexpression led to a significant growth advantage in cultured colorectal cancer cells." (PMID 31533087, 2019). "LPCAT1 may contribute to total choline metabolite accumulation via phosphatidylcholine remodeling, thereby altering the colorectal cancer lipid profile, a characteristic of malignancy, but this was investigated in a separate work as the current study focuses on ERGIC3." (PMID 23374247, 2013).
endometrial cancer (8 papers, 2020 to 2025). Primary or metastatic malignant neoplasm involving the endometrium (mucous membrane that lines the endometrial cavity). "LPCAT1 is involved in lipid metabolism a cellular process which when disrupted may be associated with increased endometrial cancer risk." (PMID 39495297, 2024). "In this study, we verified that high expression of LPCAT1 is associated with endometrial cancer." (PMID 35880567, 2022). "GPI, GPT, and LPCAT1 were frequently overamplified in endometrial cancer patients, while ADCY9 more often had missense mutations (unknown significance)." (PMID 32894095, 2020). "Our results demonstrate that silencing of LPCAT1 inhibits the growth of endometrial cancer, while overexpression of LPCAT1 results in enhanced stemness and metastasis in endometrial cancer cell lines." (PMID 35880567, 2022). "According to TCGA analysis, we found that LPCAT1 expression in endometrial cancer tissues was significantly higher than that in normal tissues." (PMID 34016103, 2021). "It is unclear how the loss of function of LPCAT1, TERT or SLC6A3 might contribute to endometrial cancer risk." (PMID 39495297, 2024). "In endometrial cancer, LPCAT1 affects the activation of the transforming growth factor (TGF)-β-Smad2/3 pathway, which may explain the effect of LPCAT1 on tumor processes in this cancer." (PMID 38893234, 2024). "Here, our results indicated that the GPL-related gene LPCAT1 had effects on the endometrial cancer TME and clinical outcomes of EC patients, which might provide a novel prognostic biomarker and immunotherapy target for EC." (PMID 34016103, 2021). "Additionally, overexpression of LPCAT1 also promoted endometrial cancer growthin vivo." (PMID 35880567, 2022). "However, LPCAT1 is reported to be involved in pyroptosis and apoptosis in various cancers, including HCC, cervical cancer, endometrial cancer, and squamous cell carcinoma of the skin." (PMID 37662906, 2023). "However, no study has demonstrated the relationship of LPCAT1 in endometrial cancer and the tumour microenvironment." (PMID 34016103, 2021).
esophageal cancer (8 papers, 2021 to 2024). A primary or metastatic malignant neoplasm involving the esophagus. "LPCAT1 has been reported to be overexpressed in esophageal cancer tissues and its interference inhibits proliferation, invasion, and metastasis of esophageal cancer cells." (PMID 37344759, 2023). "In esophageal cancer, LPCAT1 induces esophageal tumor development by influencing cholesterol metabolism through a mechanism that is different from those previously identified in esophageal tumor research." (PMID 34518524, 2021). "Our work suggests that LPCAT1 can affect cellular metastasis and regulate signal transduction pathways involved in the process, suggesting a novel role for LPCAT1 in esophageal cancer progression." (PMID 34518524, 2021). "LPCAT1 was highly expressed in esophageal cancer tissues and promoted esophageal cell invasion and migration via the SREBP-1/EGFR/PI3K signaling pathway." (PMID 34518524, 2021). "In summary, our data identify an overexpression of LPCAT1 in a subset of esophageal cancers with undifferentiated tumor grading." (PMID 34148155, 2021). "However, since LPCAT1 expression was unrelated to prognosis of patients, LPCAT1 cannot be considered as a prognostic biomarker in esophageal cancers." (PMID 34148155, 2021). "The fact, that LPCAT1 expression was enhanced in malignant as compared to benign esophageal cancer may suggest a relevant role of LPCAT1 during esophageal tumorigenesis." (PMID 34148155, 2021). "However, since LPCAT1 expression was unrelated to prognosis of patients, LPCAT1 expression cannot be considered as a prognostic biomarker in esophageal cancers." (PMID 34148155, 2021). "In esophageal cancer, one transcriptome analysis suggested an upregulation of LPCAT1." (PMID 34148155, 2021). "In this study, we found that the expression of the LPCAT1 enzyme is enriched in esophageal cancer." (PMID 34518524, 2021). "In this study, we found that LPCAT1 promoted the development of esophageal cancer." (PMID 34518524, 2021). "We further characterized the role of the lipid metabolic enzyme LPCAT1 in ESCC tumor growth and poor patient outcome and posit that LPCAT1 is a potential target for esophageal cancer diagnosis and treatment." (PMID 34518524, 2021). "However, the mechanism by which LPCAT1 regulates esophageal cancer has remained largely unknown." (PMID 34518524, 2021). "To further evaluate the potential of LPCAT1 as a prognostic biomarker in esophageal cancer, we analyzed a tissue microarray (TMA) containing more than 600 esophageal cancer specimens." (PMID 34148155, 2021). "The results of our study do not support LPCAT1 immunostaining as a prognostic marker in esophageal cancer." (PMID 34148155, 2021). "Thus, our study does not support LPCAT1 expression as a potential relevant biomarker in esophageal cancers." (PMID 34148155, 2021). "We further investigated whether LPCAT1 contributes to tumor progression in esophageal cancer; the clonogenic ability of EC9706 and TE1 cells with or without the LPCAT1 knockdown showed that LPCAT1 promoted ESCC cell proliferation." (PMID 34518524, 2021).
esophageal squamous cell carcinoma (8 papers, 2021 to 2025). Esophageal squamous cell carcinoma (ESCC) is a type of esophageal carcinoma (EC) that can affect any part of the esophagus, but is usually located in the upper or middle third. "In esophageal squamous cell carcinoma, phospholipid biosynthesis/remodeling enzyme lysophosphatidylcholine acyltransferase 1 (LPCAT1) expression is high and positively correlated with SREBP1 expression in the nucleus of tumor tissue." (PMID 36969840, 2023). "In esophageal squamous cell carcinoma, the effect of LPCAT1 on tumor processes may be related to an increase in cholesterol synthesis, which is a result of EGFR activation." (PMID 38893234, 2024). "Lysophosphatidylcholine acyltransferase 1 (LPCAT1) has been implicated in various cancer types; however, its role in esophageal squamous cell carcinoma (ESCC) remains unclear." (PMID 34518524, 2021). "In esophageal squamous cell carcinoma (ESCC), LPCAT1 regulates the upregulation of the cholesterol synthesis enzyme SQLE by promoting PI3K activation." (PMID 40145543, 2025). "Interestingly, LPCAT1 has been shown to be upregulated in various cancers, including GBM, HCC, clear cell renal cell cancer, esophageal squamous cell carcinoma (ESCC), gastric, and breast cancer." (PMID 36009491, 2022).
liver cancer (7 papers, 2021 to 2025). An epithelial or non-epithelial malignant neoplasm that arises from the liver. "Beyond its role in phospholipid metabolism, LPCAT1 also reprograms cholesterol metabolism, affecting liver cancer development." (PMID 39781455, 2025). "The core gene LPCAT1 is highly expressed in rat liver cancer tissues and promotes tumor cell sphere formation." (PMID 37717019, 2023). "It has been shown that LPCAT1 can promote endometrial tumor cell growth and stemness by affecting the TGF-β signaling pathway.In HCC, LPCAT1 is an oncogene that promotes the growth and metastasis of liver cancer cells." (PMID 37717019, 2023). "Similarly, LPCAT1 is adjacent to five enzymes related to liver cancer." (PMID 37743473, 2023).